GNAT1 (G protein subunit alpha transducin 1)
Description:
Alpha subunit of the heterotrimeric guanine nucleotide-binding protein (G protein) that transduces signals from the G protein-coupled photoreceptor rhodopsin (RHO). Required for normal RHO-mediated light perception in retinal rod photoreceptors. Functions as a GTPase that contains the guanine nucleotide binding site and cycles between an active GTP-bound state and an inactive GDP-bound state. Under dim light conditions, RHO promotes GDP release and GTP binding. Activates downstream effectors, including cone cGMP-phosphodiesterase (PDE6), to mediate the phototransduction cascade (By similarity). Stimulates PDE6 by binding and repositioning the PDE6 gamma inhibitory subunits (PDE6G) to promote catalytic activity (By similarity).
Synonyms: GNATR; CSNBAD3; CSNB1G; GBT1; HG1F
Tractability: Antibody: its Gene Ontology location is reachable by antibodies, with high confidence; UniProt places it where antibodies can reach, with medium confidence. PROTAC: ubiquitination databases record sites on it.
Gene: Protein-coding gene on chromosome 3 (50,191,610 to 50,197,696, forward strand). Ensembl gene ENSG00000114349.
Subcellular location: Photoreceptor outer segment membrane; Membrane; Photoreceptor inner segment
Subcellular location (Human Protein Atlas): End piece; Mid piece; Principal piece
Pathways (Reactome):
Sensory Perception: Activation of the phototransduction cascade; Inactivation, recovery and regulation of the phototransduction cascade
Signal Transduction: G alpha (i) signalling events
Gene Ontology:
Molecular function: acyl binding; G protein activity; G protein-coupled receptor binding; G-protein beta/gamma-subunit complex binding; GDP binding; GTP binding; GTPase activity; protein kinase binding; guanyl nucleotide binding
Biological process: detection of light stimulus involved in visual perception; phototransduction, visible light; visual perception; adenylate cyclase-modulating G protein-coupled receptor signaling pathway; negative regulation of cyclic-nucleotide phosphodiesterase activity; regulation of opsin-mediated signaling pathway; response to light stimulus; signal transduction; transducin-mediated opsin signaling pathway; cGMP catabolic process; detection of chemical stimulus involved in sensory perception of bitter taste; G protein-coupled opsin signaling pathway; G protein-coupled receptor signaling pathway; response to light intensity
Cellular component: photoreceptor inner segment; photoreceptor outer segment; cytosol; membrane; photoreceptor disc membrane; photoreceptor outer segment membrane; plasma membrane; apical plasma membrane; heterotrimeric G-protein complex; neuronal cell body; photoreceptor connecting cilium
Genetic constraint (gnomAD): Loss-of-function variants: 35 observed, 40.76 expected, observed/expected ratio (o/e) 0.86, 90% interval 0.65 to 1.14. The upper end of that interval is the gene's LOEUF score, 1.14, which puts it in group 4 of 6, group 1 being the genes least tolerant of losing a copy. Missense variants: 408 observed, 506.33 expected, observed/expected ratio (o/e) 0.81, 90% interval 0.74 to 0.88. Synonymous variants: 191 observed, 201.19 expected, observed/expected ratio (o/e) 0.95, 90% interval 0.84 to 1.07.
Gene-disease validity (ClinGen):
ClinGen rates the evidence that GNAT1 causes each of these diseases.
inherited retinal dystrophy (autosomal dominant; autosomal recessive): Definitive. An instance of retinal degeneration that is caused by an inherited modification of the individual's genome.
Homologues: Orthologues: chimpanzee GNAT1 (100% identical), macaque GNAT1 (100% identical), dog GNAT1 (99% identical), guinea pig GNAT1 (99% identical), mouse Gnat1 (99% identical), pig GNAT1 (99% identical), rat Gnat1 (99% identical), tropical clawed frog gnat1 (95% identical), zebrafish gnat1 (93% identical), Caenorhabditis elegans gpa-3 (47% identical), Caenorhabditis elegans gsa-1 (44% identical), Caenorhabditis elegans gpa-2 (43% identical), and 8 more. Paralogues in human: GNAT2 (83% identical), GNAT3 (79% identical), GNAI1 (69% identical), GNAI2 (67% identical), GNAI3 (66% identical), GNAO1 (62% identical), GNAZ (55% identical), GNA11 (51% identical), GNAQ (51% identical), GNA14 (50% identical), GNAL (45% identical), GNA15 (45% identical), and 3 more.
Diseases named in the same sentence as GNAT1 in open-access papers:
GNAT1 is named in the same sentence as 28 diseases in open-access papers, as found by Europe PMC text mining. Sharing a sentence is not in itself a finding about the gene and the disease. The quoted sentences say what the papers report.
congenital stationary night blindness (11 papers, 2013 to 2026). "GNAT1 mutations are associated with congenital stationary night blindness and impair rod photoreceptors' ability to activate phosphodiesterase-6, thereby disrupting cGMP hydrolysis and precipitating retinal degeneration." (PMID 41805095, 2026). "GNAT1 gene mutations are traditionally linked to congenital stationary night blindness (CSNB), but two cases of arRP have been reported." (PMID 39858579, 2024). "Herein we demonstrate that a genetic knock-out of Gnat1, associated with congenital stationary night blindness, slightly increases the susceptibility to light damage in mice, and this can be fully prevented by pretreatment with MET+BRM+TAM." (PMID 30947334, 2019). "GNAT1 mutations are causative for autosomal dominant or recessive congenital stationary night blindness." (PMID 30947334, 2019). "Our work confirms that the phenotype and the mode of inheritance associated with GNAT1 variants can vary from autosomal dominant, autosomal recessive congenital stationary night blindness to autosomal recessive rod-cone dystrophy." (PMID 27977773, 2016). "In rods, the α-subunit of the heterotrimeric G protein transducin is encoded by GNAT1, and patients with missense mutations in GNAT1 exhibit congenital stationary night blindness (CSNB)." (PMID 25650393, 2015). "The GNAT1 mutation has been associated with congenital stationary night blindness." (PMID 23819456, 2013). "A major novel finding from this study was the association of two genes, GNAT1 and SLC24A1, with RP that had previously only been associated with congenital stationary night blindness (CSNB)." (PMID 27624628, 2016). "Six genes encoding major components of the phototransduction cascade (RHO, GNAT1, PDE6B, GRK1, and SAG) and the regeneration of the visual pigment (RDH5) are described in congenital stationary night blindness (CSNB) patients." (PMID 24760071, 2014).
retinal degeneration (9 papers, 2009 to 2026). Degeneration of the retina. "Consistent with transducin-mediated mechanism of cell death caused by light exposure, the stress response and retinal degeneration were prevented when the Arr1−/− mice were crossed into the transducin KO (Gnat1−/−) background." (PMID 35332081, 2022). "Samples were collected from mice at 2 weeks of age and the level of rhodopsin transcripts was normalized to that of 18s rRNA or transducin (Gnat1) to account for any retinal degeneration." (PMID 38365903, 2024). "For example, many genes harboring mutations implicated in retinal degenerations characterized predominantly by night blindness–such as RHO, SLC24A1, and GNAT1–were confirmed to be selectively expressed in rods." (PMID 32555229, 2020). "The Gnat1−/− mouse is a widely used model of rod-inactivation, partly because, unlike other lesions of rod phototransduction, it lacks significant secondary retinal degeneration." (PMID 21124780, 2010). "To further investigate the role of Bax in retinal degeneration, we performed immunohistological analysis of rod transducin (Gnat1) expression in Rpe65−/− mice during the course of the disease at 2 and 6 months of age." (PMID 19672311, 2009). "Furthermore, while Gnat1−/− mice suffer slight retinal degeneration, its magnitude is much less than in other models of inherited rod dysfunction." (PMID 19898639, 2009). "Rod transducin is considered a critical element in the rod phototransduction cascade, and Gnat1−/− mice have been used as a model of rod inactivation without retinal degeneration." (PMID 19898639, 2009). "Retinal degeneration could explain the absence of a significant reduction in the level of GNAT1 protein expression shown by Western blotting, because both GNAT1 and TUBULIN levels were decreased, so the ratio was not changed." (PMID 29038159, 2017). "Retinal degeneration could explain the absence of a marked reduction of the GNAT1 protein expression level shown by Western blot analysis, because both GNAT1 and tubulin levels were decreased, so the ratio was not changed." (PMID 29038159, 2017).
night blindness (8 papers, 2016 to 2026). Inability to see clearly in dim light. "Similar to other truncating GNAT1 variants, such as p.(Gln302*) and p.(Cys321*), which have been associated with lifelong night blindness and late-onset RP, the p.(Arg253Profs*56) variant likely results in a loss of function of the transducin alpha subunit." (PMID 39858579, 2024). "In the context of patient GP2-34, the early onset of night blindness followed by slow progression of RP is consistent with other GNAT1 truncating mutations." (PMID 39858579, 2024). "Gnat1-mutated mouse models exhibit signs of night blindness and progressive degeneration of the rods over time." (PMID 39728691, 2024). "According to our case with a CNGB1 and GNAT1 mutation, mild visual symptoms, including good BCVAs, emmetropic to mild myopia, and night blindness, were documented, which were similar to prior clinical findings." (PMID 34064005, 2021). "Since rod photoreceptors are the most prevalent cell type in the retina, genes expressed in rods that are implicated in night blindness, e.g. Rho and Gnat1, have been identified as the most abundantly expressed genes in whole retinal samples from wild type mice." (PMID 29615777, 2018).
retinitis pigmentosa (3 papers, 2014 to 2021). Retinitis pigmentosa (RP) is an inherited retinal dystrophy leading to progressive loss of the photoreceptors and retinal pigment epithelium and resulting in blindness usually after several decades. "Strikingly, eight of the 67 exclusive candidates are associated with retinitis pigmentosa (human orthologues in parentheses): Gnat1 (GNAT1), Rom1a and Rom1b (ROM1), Kfharr-r2 (SAG, ARRESTIN, RP47), Rgra (RGR, RP44), Tbl2 (TBL2), Sec31b (SEC31B) and Glyr1 (GLYR1)." (PMID 34106226, 2021). "Mutations in RHO and PDE6B, but not GNAT1, are also described in retinitis pigmentosa (RP)." (PMID 24760071, 2014).
Rod-cone dystrophy (3 papers, 2016 to 2026). An inherited retinal disease subtype in which the rod photoreceptors appear to be more severely affected than the cone photoreceptors. "Recently, a homozygous truncating GNAT1 mutation was identified in a patient with late-onset rod-cone dystrophy." (PMID 27977773, 2016). "The gene Gnat1, which encodes the transducin alpha subunit, has also been implicated in CSNB and late-onset rod-cone dystrophy." (PMID 35698136, 2022).
Blindness (2 papers, 2020 to 2022). Blindness is the condition of lacking visual perception defined as a profound reduction in visual perception. "In blind mice, floor rotation resulted in a concomitant shift in the preferred firing direction of HD cells (we pooled together rd1 and Gnat1/2mut mice as results were similar between these two blindness models), suggesting that olfaction could modulate HD cell tuning." (PMID 36123333, 2022).
colorectal cancer (2 papers, 2018 to 2021). A primary or metastatic malignant neoplasm that affects the colon or rectum. "Lnc-GNAT1-1 expression significantly down-regulated in colorectal cancer and it acts as a tumor suppressor through regulating RKIP-NF-κB-Snail circuit." (PMID 29599647, 2018). "In addition, diminished expressions of lnc-GNAT1-1 were documented in colorectal cancer, and further highlighted as a promising tumor suppressor by the virtue of RKIP-NF-κB-Snail circuit regulation." (PMID 33744851, 2021).
diabetic retinopathy (2 papers, 2017 to 2023). "The deletion of GNAT1 inhibits the development of retinal vascular pathology in early diabetic retinopathy." (PMID 37098010, 2023).
retinal dystrophies (2 papers, 2019 to 2024). "The identification of the homozygous GNAT1 variant c.758_771delinsC, p.(Arg253Profs*56) in a patient with early-onset but late-progressing autosomal recessive RP (arRP) provides further support for the role of GNAT1 in retinal dystrophies." (PMID 39858579, 2024).
liver cancer (1 paper, 2020). An epithelial or non-epithelial malignant neoplasm that arises from the liver. "The present study aimed to elucidate the role of lnc-GNAT1-1 in liver cancer development and to explore the underlying mechanisms." (PMID 33193591, 2020). "Quantitative real-time polymerase chain reaction was performed to measure the expression levels of lnc-GNAT1-1 in cancerous tissues from patients with liver cancer and in liver cancer cell lines." (PMID 33193591, 2020). "However, we have not identified relevant miRNAs targeted by lnc-GNAT1-1 to exert anti-tumor effects in liver cancer; this requires further exploration." (PMID 33193591, 2020). "Nevertheless, there are no studies of lnc-GNAT1-1 in liver cancer." (PMID 33193591, 2020).
retinoblastoma (1 paper, 2025). A malignant tumor that originates in the nuclear layer of the retina. "Among the most upregulated genes were KRT5, KRT19, LCN2, SLP1 and S100A9, while GNAT1, PDE6G, WIF1, FRZB, and RHO were among the top downregulated genes in retinoblastoma." (PMID 40395327, 2025).
tumor (6 papers, 2016 to 2024). "Lnc-GNAT-1 overexpression notably decreased protein expression in Wnt/β-catenin pathway which mediates tumor cell stemness and thereby promote tumorigenesis." (PMID 39035354, 2024). "After dissection, tumor volume was measured, and a greater tumor volume was observed in the sh-lnc-GNAT1-1 group than in the control group." (PMID 33193591, 2020). "Expression levels of lnc-GNAT1-1 were determined not only in the CRC primary tumor and liver metastasis tissues, but also in the plasma of CRC patients, and its correlations with clinicopathological parameters were analyzed." (PMID 27912775, 2016). "Among the differentially expressed lncRNAs, lnc-GNAT1-1 was significantly low expressed in the liver metastasis tissues than the primary tumor site." (PMID 27912775, 2016). "Furthermore, Lnc-GNAT-1 overexpression also suppressed GC tumor growth in vivo." (PMID 39035354, 2024). "So in the present study, we decided to investigate whether lnc-GNAT1-1 could regulate the expression of RKIP, and further affect the RKIP -NF-κB-Snail circuitry to play its tumor suppressor role in CRC." (PMID 27912775, 2016).
retinopathy (2 papers, 2016 to 2026). "This work expands the phenotypic spectrum of GNAT1-associated retinopathy and identifies GNAT1 as another potential cause of a fundus sheen." (PMID 41954843, 2026). "In both situations, the mutation segregated with the retinopathy (although in the case of the GNAT1 mutation, there was only one patient who carried it homozygously and only this individual was affected in the pedigree)." (PMID 27624628, 2016).
cancer (1 paper, 2021). A tumor composed of atypical neoplastic, often pleomorphic cells that invade other tissues. "Cancer development and progression was seen to be affected by Tnfrsf1a, Adrbk2, Pld4, Gnat1 and Samsn1 in other studies." (PMID 34185104, 2021).
digestive system cancer (1 paper, 2020). A primary or metastatic malignant neoplasm involving any part of the digestive system. "Among these lncRNAs, lnc-GNAT1-1 attracted our attention because of its important effects in the progression of digestive system cancers." (PMID 33193591, 2020).
GNAT1 also shares sentences with these, for which no sentence is quoted: myopia (2 papers); autosomal recessive rod-cone dystrophy (1); cataract (1); congenital stationary night blindness autosomal dominant 3 (1); Goldmann-Favre syndrome (1); Gyrate atrophy (1); lymph node metastasis (1); Macular dystrophy (1); Oguchi disease (1); Pigmentary retinopathy (1); Retinal atrophy (1); retinal diseases (1); retinitis (1).